MIR4633 (microRNA 4633)
Synonyms: hsa-mir-4633
Gene: MicroRNA gene on chromosome 5 (129,097,688 to 129,097,766, forward strand). Ensembl gene ENSG00000264563.
Homologues: Orthologues: chimpanzee MIR4633 (100% identical).